BRCA1 (BRCA1 DNA repair associated)
Diseases named in the same sentence as BRCA1 in open-access papers (continued):
Sharing a sentence is not in itself a finding about the gene and the disease.
breast cancer (continued). "The gene that contributed most to inherited breast cancer risk in this population was BRCA2, followed by BRCA1, together accounting for more than 5% of the cases." (PMID 32318955, 2020). "Among the targets of eIF4G1-mediated translation activation post-IR is BRCA1, a tumor suppressor that facilitates error-free homologous recombination (HR) DSB repair and that causes breast cancer in humans when mutated." (PMID 32932812, 2020). "The results of these studies link the DNA repair function and maintenance of proper mammary cell differentiation function of BRCA1, highlighting the central role of BRCA1 during breast cancer evolution." (PMID 33299637, 2020). "We have previously reported that the risk of developing contralateral breast cancer is increased in BRCA1 PV carriers diagnosed with breast cancer at a very young age (<30 years at diagnosis)." (PMID 32045981, 2020). "We investigated the associations between a recently reported PRS for breast cancer, based on 313 SNPs, and a PRS for EOC, based on 30 SNPs, with cancer risks for BRCA1 and BRCA2 carriers." (PMID 32665703, 2020). "Pirouzpanah and colleagues assessed the relationship between dietary uptake of one-carbon metabolism-related nutrients and BRCA1 promoter hypermethylation and expression status in dissected breast cancer tissue samples from 146 Iranian women." (PMID 32085420, 2020). "According to the published literature, DNMT3A can mediate PTEN and BRCA1 promotor hypermethylation and decrease the expression of PTEN and BRCA1 in several cancers, including breast cancer." (PMID 32756009, 2020). "This confirms that the characteristic copy number pattern published earlier for hereditary breast cancers applies only to BRCA1-related tumors." (PMID 32164626, 2020). "Of 993 breast-cancer patients with available germline data, 22 harbored a pathogenic SNV or indel in BRCA1; 22 harbored a BRCA2 variant." (PMID 32997669, 2020). "Pathological data was available for 702 BRCA1 and 302 BRCA2 mutation carriers in the same cohort that developed a contralateral breast cancer." (PMID 32481735, 2020). "Future clinical studies using longitudinal CT‐imaging analysis of adipose tissue and muscle mass in BRCA1/BARD1‐mutant breast cancer patients are awaited to provide this key information." (PMID 32730698, 2020). "The loss of BRCA1 led to the activation of PRC2, inhibition of cell differentiation, and induction of more aggressive breast cancers." (PMID 33014839, 2020). "In our multistage study of breast cancer, 21 of 70 cases (40.0%) in the discovery stage carried 20 pathogenic variants or VUS in BRCA1/2 in Chinese women." (PMID 32879886, 2020). "Germline BRCA1 and BRCA2 mutations confer an increased lifetime risk for breast cancer and ovarian cancer." (PMID 32322271, 2020). "When data from women who developed MF/MC breast cancer were analysed in isolation, the prevalence of oestrogen receptor positivity was 85% amongst BRCA2 mutation carriers but only 15% in BRCA1 mutation carriers." (PMID 32022473, 2020). "Mutations in BRCA1 and BRCA2 genes are the mostsusceptible causes amongst the genetic risk factors that play a crucial role infamilial breast cancer." (PMID 32453341, 2020). "Another example is for the germline mutations in BRCA1 and BRCA2, in which germline mutation increases risk of hereditary breast cancer." (PMID 33256598, 2020). "CST cells share several features with BRCA1-mutant human breast cancer cell lines (HCC1937, MDA-MB-436, SUM1315MO2, and SUM149PT." (PMID 32053991, 2020). "A query for CNAs overlapping BECN1 and/or BRCA1 in ovarian cancer and breast cancer confirmed that BECN1 is occasionally exclusively deleted (no co-deletion of BRCA1, 8 of 594 tumors for ovarian cancer and 4 of 1085 for breast cancer)." (PMID 31923184, 2020).
breast cancer (continued). "The therapeutic landscape of BRCA1/2 related breast cancer has been enriched with the addition of PARP inhibitors which led to improvements in survival outcomes." (PMID 33194613, 2020). "Contrary to patients with all subtypes of breast cancer, 1748 patients with TNBC and BRCA1/2 mutations had better OS than BRCA1/2-negative ones (HR = 0.49)." (PMID 32322271, 2020). "Nonetheless, our results are in agreement with previous exome sequencing studies in non‐BRCA1/2 familial breast cancer cases." (PMID 32383162, 2020). "An increased methylation of BRCA1 is often found in the peripheral blood of breast cancer patients compared with cancer-free controls." (PMID 32013256, 2020). "Consistent with its role as a negative regulator of fatty acid synthesis, our previous study showed that BRCA1 inhibited lipogenic actions of insulin-like growth factor I (IGF-I) in breast cancer cells." (PMID 33212987, 2020). "Genotyping BRCA1, BRCA2, and PALB2 French-Canadian breast cancer variants identified a pathogenic variant in 3.8% (21/555) of breast cancer cases unselected for age or family history and 0.2% (5/1940) of cancer-free controls." (PMID 32300229, 2020). "Through single-cell RNA-sequencing, we found that Neu, PyMT and BRCA1-null mammary tumors each corresponded to a spectrum of minimally overlapping cell differentiation states without a universal BCSC population." (PMID 32840210, 2020). "Histone methyltransferase (HMT) inhibitors reduce hypermethylation of oncosuppressor genes like BRCA1 and prevent development of breast cancer." (PMID 33324554, 2020). "For example, two well-known cancer genes, BRCA1 and BRCA2, were the major genes associated with the genetic etiology of breast cancer." (PMID 32802855, 2020). "Hereditary and genetic factors, including a personal or family history of breast or ovarian cancer as well as inherited mutations (in BRCA1, BRCA2, and other breast cancer susceptibility genes) account for 5% to 10% of breast cancer cases." (PMID 32471217, 2020). "Nevertheless, pathogenic mutations in the breast cancer susceptibility genes BRCA1 and BRCA2 only account for 25–40% of familial breast cancers (FBCs) cases." (PMID 32300589, 2020). "To further investigate the metastatic function of mutated PLEKHA5 in human breast cancer, we knocked out PLEKHA5 in GFP-labeled BRCA1-WT MDA-MB-231 cells (231-GFP)." (PMID 32978388, 2020). "After running a similar analysis that combined the breast cancer and HGSOC TCGA datasets, BRCA1/2 mutations seemed to be enriched at HRD scores ≥42." (PMID 32066851, 2020). "Meanwhile, germline BRCA1 and BRCA2 mutations, as in ovarian and breast cancer, showed an increased tendency to lead to PFTC development." (PMID 32393292, 2020). "Recent studies showed that MLN4924 sensitizes the ER+ BRCA1-wild type breast cancer cell lines to radiation." (PMID 32166000, 2020). "Women who carry pathogenic mutations in BRCA1 and BRCA2 have a lifetime risk of developing breast cancer of up to 80%." (PMID 32175645, 2020). "MLN4924, a selective inhibitor of the key neddylation enzyme NEDD8 Activation Enzyme (NAE1), shows higher sensitivity to both BRCA1-wild type and -mutant TNBCs compared to other breast cancer subtypes." (PMID 32166000, 2020). "BRCA1 (Breast Cancer 1): Gene expression levels for all cybrids (L, [A+B], and D) did not significantly change after treatment with cisplatin compared to untreated-control cybrids (n = 7, n = 4, n = 3, p = 0.356, p = 0.294, p = 0.158, respectively)." (PMID 33062421, 2020). "(B) t-SNE plots of mammary tumor cells colored by tumor sample; Neu (blue), PyMT (green), BRCA1-null (red)." (PMID 32840210, 2020). "Cisplatin has been reported to be effective and generally well tolerated among Polish BRCA1 patients with breast cancer." (PMID 32824581, 2020).
breast cancer (continued). "Akt is the main target gene of PI3K, and its silencing can cause a decrease of BRCA1 protein in different types of breast cancer cells, suggesting that PI3K pathway can regulate the expression level of BRCA1." (PMID 33817238, 2020). "As the rate of mutations in BRCA1 and BRCA2 genes was nearly about 20% among female breast and ovarian cancers, BRCA1 was one of the most significant susceptibility genes in breast cancer." (PMID 32470015, 2020). "Breast cancers in BRCA2 carriers are predominantly ER-positive, in contrast to BRCA1 carriers, who mainly present with basal-like (ER-negative) breast cancers." (PMID 32939053, 2020). "The pathogenesis of breast cancer is influenced by the DNA methylation of miRNA genes, with BRCA1 functionality reduction inducing global hypomethylation." (PMID 33194751, 2020). "In this study, of consecutive breast cancer cases with up to 20-years of follow-up, the annual rate of contralateral breast cancer overall was 0.6% but increased to 2%–3% per year among BRCA1/2 PV carriers." (PMID 32045981, 2020). "Altogether, we identified a genetic modifier that protects against breast cancer in women who carry pathogenic mutations in BRCA2 (P = 0.0008) and to a lesser extent BRCA1 (P = 0.02)." (PMID 32175645, 2020). "BRCA1 is occasionally exclusively deleted even less frequently (3 of 594 for ovarian cancer and 4 of 1085 for breast cancer)." (PMID 31923184, 2020). "Genetic alterations in the breast cancer 1 (BRCA1) and breast cancer 2 (BRCA2) pathway comprise the largest number of relevant genomic alterations in high-grade ovarian serous cancers (HGSCs)." (PMID 32403357, 2020). "Mutations in the genes BRCA1 and BRCA2 represent a significant risk factor for ovarian and breast cancer." (PMID 32719921, 2020). "Several mutations, including those in BRCA1, BRCA2, ATM, CHEK2, and PALB2, have been associated with the clinicopathological features exemplified by the breast cancer subtype and tissue of origin for additional cancers." (PMID 32566746, 2020). "A mutation variant within the 3’-untranslated region (3’-UTR) of the BRCA1 gene and the VEGF -2578AA genotype were found to be associated with increased risk of breast cancer in among Saudi females." (PMID 32711446, 2020). "BRCA1 and BRCA2 genes are found to be strongly associated with breast cancer and the frequency of these genetic mutations varies among ethnic groups and countries." (PMID 32856854, 2020). "In this article, we demonstrate that BRCA1 promoter methylation, analyzed in a large cohort of 1031 primary breast tumors, predicts improved breast cancer–specific survival outcomes in patients treated with cytotoxic chemotherapy." (PMID 32175521, 2020). "Similar to that in many BRCA1- and BRCA2-associated tumors, many PALB2-associated breast cancers (i.e., 67%) show loss of the PALB2 wild type allele via acquired pathogenic somatic variants, or via loss-of-heterozygosity (LOH)." (PMID 33195396, 2020). "An important recent finding concerning the role of miR-155 in breast cancer is its relationship with BRCA1." (PMID 33273900, 2020). "While BRCA1 carriers predominantly present with high-grade hormone receptor-negative invasive breast cancer, BRCA2 mutation carriers have more luminal breast cancers and a higher proportion of DCIS, sometimes only detected as mammographic calcifications." (PMID 32333294, 2020). "BRCA1, BRCA2, and PALB2 are established breast cancer predisposition genes conferring high risk especially for ER-negative disease and TNBC." (PMID 31991861, 2020).
breast cancer (continued). "According to a previous study, specific activation of AKT-1 is a contributor to EZH2-induced phenotype, and the overexpression of EZH2 induces activation of AKT-1 and BRCA1 inhibition in breast cancer, which was consistent with our findings." (PMID 31830649, 2020). "BRCA1 and BRCA2 are highly penetrated genes involved in the familial breast cancer development and about 15 % of all familial breast cancer can be attributed to a mutation in these genes." (PMID 33013205, 2020). "The CpG methylation status of breast cancer related genes (BRCA1, CDH1, PTEN, and CCND2) is also increased." (PMID 33330580, 2020). "Since CD14 protein expression can be detected in a subset of BRCA1-null mouse tumor cells, as well as human breast cancers, further work will be necessary to validate its potential significance in human breast cancer." (PMID 32840210, 2020). "(A) Schematic of workflow for the isolation of mammary tumor cells from BRCA1-null, PyMT and Neu tumors for scRNA-seq." (PMID 32840210, 2020). "The prevalence of pathogenic/likely pathogenic BRCA1/BRCA2 gene mutations among patients with TN disease was 33.9%, and it was 60% among patients with both TN disease and a family history of breast cancer." (PMID 32083950, 2020). "Since PARPi were approved by the FDA and EMA as a therapeutic strategy for advanced BRCA1/2-mutant breast cancer, the resistance to PARPi has been the principal obstacle limiting the clinical use in TNBC." (PMID 33324554, 2020). "Various studies demonstrated that PARP inhibitors had promising results in clinical trials for BRCA1/2-mutant tumors, such as breast cancer, ovarian cancer, pancreatic cancer, and prostate cancer." (PMID 32883316, 2020). "To address this, we selected 19 non‐BRCA1/2 breast cancer families in which at least three siblings were affected, while no first‐degree relatives of the previous or following generation had breast cancer." (PMID 32383162, 2020). "According to our selection criterion of variants, 20 potentially pathogenic variants containing 9 variants in BRCA1 and 11 variants in BRCA2 were detected in at least one case from 70 familial breast cancer cases." (PMID 32879886, 2020). "Germline pathogenic variants in BRCA1 and BRCA2 increase cumulative lifetime risk up to 75% for breast cancer and 76% for ovarian cancer." (PMID 33081408, 2020). "On the other hand, the breast cancer susceptibility genes, BRCA1 and BRCA2, also known as FANCS and FANCD1, respectively, are involved in the FA pathway; hence, researchers have studied the association between the FA pathway and cancer predisposition." (PMID 32300589, 2020). "To validate the therapeutic relevance of KLF4 in breast cancer DNA repair/DNA damage targeting treatment, we have conducted an in vivo mouse xenograft study by using murine 4T1 model, which harbors wild‐type BRCA1 expression." (PMID 33231937, 2020). "Our findings, taken together, suggest that HFD-induced obesity chronically establishes a tumorigenic microenvironment to promote breast cancer development through the modifications of ECM homeostasis and the immune ecosystem in the BRCA1-mutated mammary gland." (PMID 32785175, 2020). "In a previous study, we have sequenced the entire coding region of HOXB13 in 1,250 familial non-BRCA1/2 breast cancer cases and 800 controls." (PMID 32546843, 2020). "Together, mutations in the BRCA1 and BRCA2 genes contribute to about 20–25% of inherited breast cancers." (PMID 32824813, 2020).
breast cancer (continued). "High-penetrance breast cancer genes, such as BRCA1 and BRCA2, are routinely diagnosed in clinical practice in many countries." (PMID 32823908, 2020). "BRCA1 deficient cells are highly sensitive to PARP and DNA methyltransferase inhibition in comparison with wild-type BRCA1 cells, resulting in clinical trials in breast cancer patients to test the efficiency of these drugs." (PMID 32856871, 2020). "In this study, we analyzed the single-cell transcriptomes of 11639 mammary tumor cells from three prominent mouse models of breast cancer (BRCA1-null, PyMT, Neu)." (PMID 32840210, 2020). "We analyzed germline variants of 11 breast cancer susceptibility genes for 1,995 Japanese breast cancer patients, and identified 101 (5.1%) pathogenic variants, including 62 BRCA2 and 15 BRCA1 mutations." (PMID 33067557, 2020). "The relationship between ERβ and BRCA1 in breast cancer still needs further basic research to verify." (PMID 32944243, 2020). "Loss of heterozygosity eliminates the wild-type allele in proliferative female tissues, which preferentially use the homologous recombination pathway, giving rise to the striking tissue tropism seen in BRCA1 breast cancer." (PMID 33142801, 2020). "Earlier, in vitro data in breast cancer cell lines demonstrated an increase in BRCA1 and BRCA2 mRNA expressions with DHA treatment, suggesting a transcriptional or post-transcriptional regulation of these genes by DHA." (PMID 32498320, 2020). "Dysfunction of BRCA1-mediated DNA repair in PRMT1-silenced breast cancer cells was also evidenced by monitoring 53BP1 foci formation in irradiated cells." (PMID 32764667, 2020). "Much of the hereditary component of breast cancer remains unexplained, with pathogenic variants in moderate- and high-risk genes, such as BRCA1 and BRCA2 (BRCA1/2), accounting for less than 25% of the familial risk for the disease." (PMID 32066492, 2020). "It is noteworthy that BRCA1 c.3257del was recurrent in three unrelated cases among sporadic breast cancer cases." (PMID 32879886, 2020). "Aberrant BRCA1 promoter methylation is seen in 5%–30% of ovarian cancers and in 11%–14% of sporadic breast cancer." (PMID 32481735, 2020). "BRCA1 and BRCA2 act as tumor suppressor proteins, and patients with inherited mutations therein are more likely to develop aggressive breast cancers." (PMID 32824813, 2020). "Through topological analysis scores of the PPI network and 43 overlapping genes, we sought to select some genes, thereby using survival analysis and diagnostic value assessment to identify key genes pertaining to BRCA1/2-mutant breast cancer." (PMID 31998560, 2020). "For example, the Tyr37Ala mutant in BRCA1 lack ligase activity, being therefore incapable of reversing γ-radiation hypersensitivity of BRCA1-null human breast cancer cells." (PMID 32117970, 2020). "The PRS developed for predicting ER-negative breast cancer showed the strongest association with breast cancer risk for BRCA1 carriers, while for BRCA2 carriers the PRS developed for predicting overall breast cancer risk performed best." (PMID 32665703, 2020). "For example, AKT silencing restored formation of IR-induced BRCA1 foci in breast cancer cells, whereas HR-related proteins (e.g., BRCA1 and Rad51) sequestered in the cytoplasm upon activation of AKT1." (PMID 33266502, 2020). "Carriers of BRCA1 mutations have a 70–80% chance of developing breast cancer, while those carrying BRCA2 mutations have a 40–84% risk of breast cancer." (PMID 33324554, 2020). "TNBC accounts for about 70% and 16–23% of BRCA1 and BRCA2 mutation carriers, respectively, suggesting that TNBC is also inextricably linked to germline mutation in this breast cancer susceptibility gene." (PMID 31998560, 2020).